CX3CL1 (C-X3-C motif chemokine ligand 1)
Diseases named in the same sentence as CX3CL1 in open-access papers (continued):
Sharing a sentence is not in itself a finding about the gene and the disease.
tumor (continued). "This short interference with VEGF-A signalling triggered upregulation of CX3CL1 expression in blood vessels of DLD1 xenografts without affecting the tumour vessel density or tumour size." (PMID 29367702, 2018). "Furthermore, a recent study has shown that CX3CR1, a receptor for CX3CL1, is exclusively expressed in a subset of CD8+ effector memory T cells infiltrating tumor tissues in patients responding to anti-PD-1 therapy." (PMID 30108590, 2018). "The CX3CL1 expressed by GB cells induces the human GAMs recruitment through its receptor CX3CR1 and increases the expression of matrix MMPs 2, 9, and 14 in GAMs, which consequently promotes the tumor invasion." (PMID 30123112, 2018). "Here we identified CX3CL1 as the common chemokine-mediating spine metastases, which is independent of tumor type." (PMID 28122354, 2017). "No statistically significant main effects of tumor or interactions with time were evident for other inflammation-related genes (Il-6, Ccl5, Ccl1, Ccl22, Cx3cl1; p>0.05)." (PMID 27548621, 2016). "These analyses revealed that the tumours are characterized by expression of inflammatory chemokines (CCL2, CCL5, CCL7, CCL8, CCL12, CXCL9, CXCL10 and CX3CL1), reflected by an enrichment of activated Foxp3− and Foxp3+ T cells expressing T helper type 1-associated chemokine receptors." (PMID 25495686, 2015). "Each of these chemokines was consistently expressed in all of the MCA-induced tumours tested and expression of most, namely CCL2, CCL7, CCL8, CCL12 and CX3CL1, was detectable only in the tumours and not in spleen and lymphoid tissue." (PMID 25495686, 2015). "CX3CL1-driven chemotaxis and adhesion are mediated by CX3CR1 that is expressed on different cell types such as NK cells, CD14+ monocytes, cytotoxic effector T cells, B cells, neurons, microglia, smooth muscle cells, and tumor cells." (PMID 24799766, 2014). "The biological activities of CX3CL1 are mediated by CX3CR1, that is expressed on different cell types such as NK cells, CD14+ monocytes, cytotoxic effector T cells, B cells, neurons, microglia, smooth muscle cells, and tumor cells." (PMID 24799766, 2014). "Expression of both CX3CL1 and CX3CR1 influences the clinical features and prognosis in patients with HCC since high expression of the chemokine/receptor axis correlates with better prognosis and tumor differentiation." (PMID 24799766, 2014). "DNA vaccine co-expressing HIV-1-RT antigen and CX3CL1-Ig promoted enhanced tumor rejection compared to DNA vaccine without CX3CL1-Ig." (PMID 24967094, 2013). "Hierarchical clustering analysis, including age at diagnosis, tumor grade, FIGO stage, Ki-67 index, CX3CL1, SDF-1/CXCL12 and GILZ immunostaining scores, distinguished two major clusters corresponding to low and high levels of proliferation and differing in terms of GILZ and CX3CL1 expression." (PMID 21750716, 2011). "In line with this hypothesis, we showed that the constitutive production of CX3CL1 by malignant epithelial ovarian cells led to the release of the soluble form of this chemokine, which binds to CX3CR1 present on tumor cells." (PMID 21750716, 2011). "Moreover, the upregulation of SIRT1 and CX3CL1 was significantly correlated with several aggressive clinicopathological features of CRC, including advanced tumor stage, increased lymphatic and distant metastasis rates, and increased tumor invasion depth." (PMID 39783838, 2025). "However, even in HGSOC itself, this distinguishes CX3CL1 from other T-cell recruiting chemokines such as CXCL9 and CXCL10, which can combat tumour growth in vivo by enhancing lymphocyte infiltration and represent a strong and robust protective prognostic marker." (PMID 39862711, 2025). "Cx3cl1 overexpression, however, had no impact on tumour cell proliferation in vitro." (PMID 39862711, 2025).
tumor (continued). "With progressive ADM expression decline, transcriptional levels of pro-tumorigenic inflammatory cytokines IL1B and CX3CL1 demonstrated gradual downregulation, suggesting elevated ADM expression may accelerate tumor progression through pro-inflammatory microenvironment enrichment." (PMID 41450464, 2025). "Moreover, the addition of CX3CL1 to non-immunogenic doses of MTX-treated dying cancer cells in mouse prophylactic tumour vaccination models resulted in the activation of an adaptive immune response and effectively lengthened survival." (PMID 39011040, 2024). "It is important to remark that anti-tumor properties have been described for sFKN, while, in some cancers, it has been shown that membrane-bound FKN promotes metastasis of CX3CR1+ cancer cells towards sites with elevated CX3CL1 expression, such as lungs, bones, and others." (PMID 39125578, 2024). "Importantly, a trend for increased mRNA expression of CX3CL1 and CXCL10 in tumor cells was also observed upon dabrafenib treatment in vivo, suggesting that such a recruitment could take place in vivo." (PMID 38630384, 2024). "However, due to the elevated concentration of CX3CL1, cancer cells expressing CX3CR1 might also be retained within the tumour and become the target of immune cells." (PMID 39011040, 2024). "However, no comprehensive investigation of CX3CL1 across all The Cancer Genome Atlas (TCGA) tumor types has been performed." (PMID 37153002, 2023). "In addition, CX3CL1 increased the secretion of platelet-derived factor 4 (PDF-4)/CXCL4 in macrophages and cooperated with MMP9 released by stromal cells to support tumor angiogenesis, which further accelerated the accumulation of monocytes from peripheral blood." (PMID 37968706, 2023). "The CX3CR1-positive tumor cells could adhere to nearby infiltrating ganglia and neural cells expressing CX3CL1, which were preferred to local rather than distant tumor in human PDAC." (PMID 35478937, 2022). "The microarray data of patients with ccRCC from the GSE53757 (P < 0.001) and GSE40435 (P < 0.001) cohorts further validated the CX3CL1 expression difference between tumor and non-tumor tissue samples; the expression of CX3CL1 was significantly higher in tumor tissues than in normal tissues." (PMID 36397015, 2022). "At the same time, our results indicate that CX3CL1 can restore or enhance the anti-tumor activity of activated CD8+ T cells in the tumor immune microenvironment and, thereby, reshape the tumor immune microenvironment to improve the anti-tumor immunity of advanced ccRCC." (PMID 36397015, 2022). "Contrary to our results, a previous study suggested that CX3CR1 (lack of the allele I249) might play a limited or insignificant role in CRC, and plasma FKN/CX3CL1 does not appear to be a valuable tumor marker in CRC." (PMID 35140706, 2021). "However, trastuzumab treatment attenuated tumor growth of both MDA-MB-453CX3CL1 and empty vector transfected MDA-MB-453 transplanted mice but showed enhanced efficiency especially in preventing lung metastases in CX3CL1 overexpressing cancer cells." (PMID 34070094, 2021). "However, non-classical monocytes can be recruited to a tumor by CX3CL1, where they perform proangiogenic roles." (PMID 32466280, 2020). "To further characterize whether the CX3CL1-induced activation of Src/P115-RhoGEF/ROCK signaling in VMECs plays an important role in the TEM of cancer cells, we monitored changes in the TEM rate of fluorescently labeled tumor cells across VMEC monolayers." (PMID 32390803, 2020). "Another study showed that the use of ex vivo adenovirus vector in increasing CX3CL1 expression in dendritic cells and introducing these cells into a tumor increased the anti-tumor response, in particular the homing of CD8+ T cells and CD4+ T cells to the tumor." (PMID 32466280, 2020).
tumor (continued). "Importantly, CX3CL1-induced stress fiber formation in VMECs via activation of the Src/p115-RhoGEF/ROCK signaling pathway, which plays an important role in VMEC monolayer hyper-permeability and tumor cell high TEM in the spine." (PMID 32390803, 2020). "Furthermore, our results confirmed that the main resource of CX3CL1 is tumor cells, not endothelial cells or other stromal cells." (PMID 31367257, 2019). "Using SCT cells, which are derived from the skin of p16Ink4a knockout mice and are highly expressing CX3CL1, we showed that treatment with anti-CX3CL1 exerted significant suppressive effects against tumour progression, which has not been previously demonstrated in vivo." (PMID 29234059, 2017). "Based upon these findings, we have proposed a model whereby the CX3CR1/CX3CL1 axis may contribute to interactions between CLL cells and tumor microenvironment by increasing CXCL12-mediated attraction of leukemic cells to NLC and promoting directly adhesion of CLL cells to NLC." (PMID 24799766, 2014). "However, there are also a small number of chemokine and GPCR interactions that may inhibit tumor cells invasion, such as CX3CR1/CX3CL1 interaction in glioma." (PMID 25110692, 2014). "However, we can no longer exclude that CX3CL1 also contributes to other aspects of tumor biology, including immune cell recruitment and the anti-tumor response." (PMID 21750716, 2011). "Furthermore, we demonstrated that the addition of CX3CL1 to a non-immunogenic dose of MTX-treated dying cancer cells is sufficient to elicit an immunogenic response in a tumour prophylactic mouse model, thereby revealing CX3CL1 as a power switch of immunogenic apoptosis induced by MTX." (PMID 39011040, 2024). "Furthermore, the addition of 1 ng or 10 ng of recombinant CX3CL1 (rCX3CL1) to a non-immunogenic dose of dying/dead cancer cells for prophylactic vaccination of mice significantly increased the tumour-free survival of mice and restored immunogenicity of dying cancer cells." (PMID 39011040, 2024). "Hence, the release of CX3CL1 by the MTX-induced dying cancer cells may establish a gradient directed towards the tumour, presumably augmenting CX3CR1+ immune cell migration along the gradient and activation of an anti-tumour immune cycle." (PMID 39011040, 2024). "Despite the possible role of CX3CL1 in tumor progression in spine, the effects of CX3CL1 on several aspects of NSCLC spinal metastasis, particularly on CTC extravasation to vertebral cancellous bone, which is the first and crucial step for tumor spinal metastasis, remain unknown." (PMID 33754027, 2021). "We observed a lower CX3CL1+/PANCK+ ratio in adjacent noncancerous tissues and low‐grade tumor tissues, while the CX3CL1+ tumor cell ratio was significantly greater in high‐grade tumor tissues." (PMID 39783838, 2025). "Meanwhile, non-transcriptional activity of HIF-1α reduces CX3CL1 degradation, while IL-15Rc reduces both HIF-1α and CX3CL1 levels in tumor cells." (PMID 38279145, 2024). "This analysis led to the identification of the genes CX3CL1, CCL28, PROM1, and KLK5, which were highly expressed in the boundary cells and not in tumor cells, myoepithelial cells or any other colocalized cell type." (PMID 38114474, 2023). "Significantly, CX3CL1 is not the only chemokine involved in this process, e.g., also important in the recruitment of microglia to GBM tumor are MCP-1/CCL2 and RANTES/CCL5." (PMID 32466280, 2020). "CX3CL1 from apoptotic bodies can act on TAM and influence the distribution of these cells inside the tumor, which seems to be only local, although no thorough research has been conducted in this regard." (PMID 32466280, 2020). "This would help explain the fact that tumor cells up-regulate CCL2 to attract monocyte infiltration into GBM, while on the other hand they do not express CX3CL1." (PMID 25987130, 2015).
tumor (continued). "Remarkably, our findings from the tumour prophylactic vaccination experiments demonstrate that only lower doses (1 ng or 10 ng) of CX3CL1 exhibit an enhanced anti-tumour effect of ICD, whereas use of a high dose (100 ng) leads to almost complete absence of the anti-tumour effect." (PMID 39011040, 2024). "Moreover, the addition of recombinant CX3CL1 to non-immunogenic doses of MTX-treated, apoptotically dying cancer cells in the murine prophylactic tumour vaccination model induced a robust immunogenic response, effectively increasing the survival of the mice." (PMID 39011040, 2024). "Interestingly, the highest CX3CL1 expression levels were found in grades III–IV tumors: oligodendrogliomas, anaplastic astrocytomas and glioblastomas, and correlated inversely with patient overall survival, but the receptor was present in similar levels, independent of tumor grade." (PMID 32456359, 2020).
cancer (133 papers, 2010 to 2026). A tumor composed of atypical neoplastic, often pleomorphic cells that invade other tissues. "Although CX3CL1 has been implicated in bone metastasis and cancer cell growth and invasion, a different result has been reported in relation to overall survival." (PMID 40508161, 2025). "The role of CX3CL1 has been linked to a higher risk of disease recurrence and cancer-specific death." (PMID 39409924, 2024). "Among the chemokine-related genes associated with all categories, Cx3cl1 emerged as a significantly upregulated gene in aggressive MOC2 cancer." (PMID 38775151, 2024). "To evaluate an association between the functional domains of CX3CL1 in cancer and the cervical LN metastasis and lymphangiogenesis, we analyzed the change in lymphatic vasculature landscape in MOC2Δs-CX3CL1 and MOC2Δcd-CX3CL1 tumors." (PMID 38775151, 2024). "CX3CL1 has been described as an important chemokine that can be implicated in the context of cancer, although controversies persist regarding the properties and activities of this chemokine due to its pro- and anti-cancer characteristics." (PMID 39011040, 2024). "As determined by pan-cancer prognostic analyses, high expression of CX3CL1 was substantially associated with improved OS, DSS, and PFI in CESC and KICH, OS and DSS in KIRC, and DSS and PFI in LUAD." (PMID 37153002, 2023). "Next, I attempted to determine the association between the CX3CL1 expression and certain pathological stages within various cancers." (PMID 37153002, 2023). "CX3CL1 gene mutations were found in 23 of 33 TCGA cancer types, including 8 types in the upregulated group and 4 types in the downregulated group." (PMID 37153002, 2023). "As determined by the Kaplan-Meier method of estimating survival, high CX3CL1 expression was associated with either favorable or unfavorable outcomes depending on the different types of cancer." (PMID 37153002, 2023). "In conclusion, our study performed a systematic, pan-cancer analysis of CX3CL1, assessing the potential association between CX3CL1 expression and clinical outcomes, pathological stages, and immune cell infiltration in a wide range of cancer types." (PMID 37153002, 2023). "Seventy percent of TCGA cancer types had CX3CL1 mutations, of which more than half were significantly associated with CX3CL1 expression." (PMID 37153002, 2023). "Approximately 45% of TCGA cancer types were associated with CX3CL1 methylation, and 60% of these cancer types displayed significant differential CX3CL1 expression." (PMID 37153002, 2023). "In this study, by exploring the expression of CX3CL1 pan-cancer and its association with prognosis, we determined that CX3CL1 is involved in the development of ccRCC and the survival of patients with ccRCC." (PMID 36397015, 2022). "Patients with high expression of CX3CL1 had an ~2-fold increased risk of cancer-specific death based on univariable (HR=2.16, 95%CI: 1.59-2.93, P<0.001) and multivariable (HR=2.17, 95%CI: 1.08-2.39, P=0.006) analyses." (PMID 34671562, 2021). "The results showed that CX3CL1 overexpression was independently and significantly associated with poor prognosis (increased risk of recurrence and cancer-specific death rate)." (PMID 34671562, 2021). "Due to the high expression of CX3CL1 in bones, lungs and nervous tissues, circulating cancer cells with CX3CR1 expression cause metastasis in these organs and tissues." (PMID 32466280, 2020). "Accordingly, targeting TAMs via the CSF1/CSF1R or CX3CL1/CX3CR1 signaling pathway is an attractive therapy for cancers associated with increased numbers of TAMs (reviewed in refs.46,47)." (PMID 30237497, 2018). "Our present study showed that CX3CL1 is associated with the process of spinal metastases from different primary cancers." (PMID 28122354, 2017). "Deletion of CX3CL1 in cancer cells reduces myeloid cell infiltration associated with Vhl deficiency, and Vhl deficiency may contribute to altered immune status." (PMID 40508161, 2025).